JAG1 (jagged canonical Notch ligand 1)
Diseases named in the same sentence as JAG1 in open-access papers (continued):
Sharing a sentence is not in itself a finding about the gene and the disease.
breast carcinoma (continued). "The immunoblot analysis further confirmed the protein expression of YAP1 and JAG1 in both breast cancer cells, which gave the same results as RT-PCR." (PMID 32046779, 2020). "Meanwhile, we found that the siRNA-mediated JAG1 knockdown impairs the secretion and expression of IL-4 and IL-6 of breast cancer cells." (PMID 32943090, 2020). "After knocking down linc-OIP5 in breast cancer cells, JAG1 expression was downregulated while DLL4 expression was upregulated in co-cultured HUVECs, rendering the production of fewer blood vessels." (PMID 32046779, 2020). "The in vivo experiments showed that the tumor volumes of mouse primary breast cancer were obviously smaller after the subcutaneous injection of the 4 T1 cells which were transfected with STAT3 siRNAs (Si-STAT3) or JAG1 siRNAs (Si-JAG1)." (PMID 32943090, 2020). "The siRNA-mediated STAT3 knockdown or JAG1 knockdown markedly inhibited the invasion of breast cancer cells." (PMID 32943090, 2020). "JAG1 mRNA expression is upregulated in breast cancer and has been correlated with a poor overall breast cancer survival." (PMID 31354524, 2019). "We were also able to detect an increase in macrophage (mouse) JAG1 mRNA expression when human MDA-MB 231 breast cancer cells were co-cultured with macrophages." (PMID 29636067, 2018). "Downregulation of JAG1 or blocking Notch with GSI in a metastatic breast cancer model (MDA-231) attenuates bone metastasis by reducing osteolysis in the bone microenvironment." (PMID 30515368, 2018). "Both gal-3 and JAG1 are overexpressed in several malignancies such as prostate cancer, breast cancer, glioma and head and neck cancers and are largely appreciated as potential targets for cancer therapy, including antiangiogenic therapy." (PMID 28533486, 2017). "To rule out the cell line-specific effect, we inhibited KDM2A in SkBr3 breast cancer cells and found the expression of JAG1 and PDGFA was also reduced." (PMID 27029061, 2016). "Taken together, we conclude that KDM2A functions as an oncogene in breast cancer by upregulating JAG1 to promote stemness, chemoresistance and angiogenesis." (PMID 27029061, 2016). "In consistent with their results, we also found that JAG1-expressing breast cancer cells activated the NOTCH signaling and increased tube formation in endothelial cells." (PMID 27029061, 2016). "Collectively, we conclude that KDM2A functions as an oncogene in breast cancer by upregulating JAG1 to promote stemness, chemoresistance and angiogenesis." (PMID 27029061, 2016). "We showed for the first time that KDM2A binds to the JAG1 promoter to increase its expression in breast cancer cells." (PMID 27029061, 2016). "Our results suggested that KDM2A upregulates JAG1 to promote NOTCH activation which directly activates the transcription of SOX2 gene in breast cancer cells." (PMID 27029061, 2016). "In line with this, we found that several of the most upregulated genes in long-term EMT cells including Tnc, Mmp9, Jag1, and Ret, are known to promote breast cancer metastasis." (PMID 25674539, 2015). "In breast cancer, high levels of JAG1 promote stem cell self-renewal and potentiate mammosphere formation in vitro." (PMID 25309874, 2014). "These subtypes of breast cancers generally have higher levels of JAG1 expression, which correlate with reduced disease free survival (DFS)." (PMID 25309874, 2014). "JAG1-induced signaling in breast cancer inhibits the epithelial phenotype via upregulation of the EMT master-regulator SLUG, and promotes tumor growth and metastasis." (PMID 25309874, 2014). "Our work demonstrated that ECs Jag1/notch mediated interaction with breast cancer cells increased their tumorigenicity, stemness and invasiveness." (PMID 25380486, 2014). "Our gene expression analysis also supported themesenchymal-basal specific expression of Jag1, which is particularlypronounced in breast cancer." (PMID 25380226, 2014).
breast carcinoma (continued). "Studies indicate that JAG1 is the most prominent ligand involved in this aberrant Notch activation in breast cancer." (PMID 25309874, 2014). "Leptin, OB-R, Notch4, JAG1 and, IL-1R tI were detected in more than 60% of breast cancer (ER+, ER- and, TNBC)." (PMID 24716804, 2014). "The analysis of univariate association of categorized and continuous A_HSCOREs of NILCO and targets showed that Notch1 and JAG1 expression were significantly higher in breast cancers positive for Ki67 (p=0.01 and p=0.004 respectively)." (PMID 24716804, 2014). "E2 promoted 8-fold and 6-fold increase in Notch1 and JAG1 expression, respectively, in breast cancer MCF-7 cells." (PMID 21731759, 2011). "In our study, miR-34b has been showed to inhibit cell growth by targeting cyclin D1 and JAG1, both of which are crucial genes covering various types of breast cancer." (PMID 22113133, 2011). "In agreement with mouse experiments, high expression of JAG1 and HEY1 are associated with better overall survival among patients with luminal tumors, whereas high expression of JAG1 and HEY2 are both associated with worse overall survival in basal subtype of human breast cancer." (PMID 39890784, 2025). "In breast cancer, JAG1 has been confirmed to induce tumor angiogenesis and tumor growth." (PMID 35332121, 2022). "To further study this possibility, we decided to analyze the expression levels of the JAG1, which encodes for Jagged1, one of the most important canonical NOTCH receptor ligands in breast cancer, as well as the expression levels of the four NOTCH receptor genes in our DLK2-overexpressing cells." (PMID 35163478, 2022). "JAG1 is significantly up-regulated in gastric cancer and breast cancer." (PMID 35349480, 2022). "Moreover, BRCA1 and ΔNp63 contribute to the regulation of stemness and differentiation signaling in breast cancer by joint up-regulation of the Notch ligand Jagged-1 (JAG1)." (PMID 34638302, 2021). "Similarly, the Dll1, Jag1 mediated survival is responsible for chemoresistance in breast cancer and multiple myeloma." (PMID 33968932, 2021). "Breast cancer cells with high JAG1 mRNA and protein levels are more aggressive." (PMID 32943090, 2020). "After co-culturing human breast cancer cell lines (MDA-MB-231, MDA-MB-468, and MCF-7) with PMA-induced human monocyte THP-1 cells for 48 h, we found that either STAT3 knockdown or JAG1 knockdown in breast cancer cells reduced the relative mRNA levels of CD206 and CD163 in THP-1 derived macrophages." (PMID 32943090, 2020). "We also performed these experiments in a coculture system of SUM-159 with HUVEC-mCherry and obtained similar results, confirming that endothelial Jag1-induced juxtacrine activation of the Notch1 receptor leads to increased Zeb1 expression in breast cancer cells." (PMID 33046710, 2020). "Therefore, Zeb1 depletion in breast cancer cells impairs VEGFA paracrine signaling in adjacent endothelial cells to subvert a Jag1-mediated perivascular niche." (PMID 33046710, 2020). "In addition, STAT3 knockdown or JAG1 knockdown reduced the secretion and protein expression of IL-4 and IL-6 in breast cancer cells, it also inhibited the proliferation of breast cancer cells." (PMID 32943090, 2020). "E2 can induce Jag1 and Notch1 expression in breast cancer MCF7 cells; increased Jag1 is abrogated by ER antagonist treatment, suggesting an ER-dependent mechanism corroborated by the discovery of imperfect oestrogen-responsive elements in the 5′ region of Notch1 and Jagged1 genes." (PMID 31868216, 2019). "JAG1-Notch signaling leads to Cyclin-D1 induction, a gene that is essential for normal breast development in mice and frequently deregulated or amplified in human breast cancer." (PMID 30515368, 2018).
breast carcinoma (continued). "Overexpression of Notch-1 receptor and ligand JAG1 supports the maintenance of breast cancer stem cells (CSCs) and was crucial for cell survival, apoptotic inhibition, proliferation, adhesion, angiogenesis, metastatic potential, poor prognosis, relapse, and drug resistance in TNBCs." (PMID 30248941, 2018). "High expression of Notch1 and JAG1 correlate with poor prognosis in lung and breast cancer." (PMID 30004402, 2018). "Moreover, diet-induced obesity, which increased leptin levels and signaling in mice hosting mammary tumors, incremented the levels of Notch3, JAG1 and survivin." (PMID 30004402, 2018). "Moreover, it has been demonstrated that high expression of JAG1 shows a correlation with breast cancer metastasis." (PMID 29104587, 2017). "Furthermore, NOTCH1 has been identified as a mediator of the RAS oncogenic pathway; this is often deregulated during the early stages of breast cancers and participates in the JAG1/NOTCH1/CCND1 axis critical for maintaining proliferation of TN BC cells." (PMID 27888801, 2017). "The involvement of JAG1 in cell proliferation has also been described in breast cancer stem cells." (PMID 27855169, 2016). "Knockdown of KDM2A in breast cancer abolished these stimulatory effects which could be reversed by JAG1 overexpression indicating JAG1 is involved in KDM2A-induced tumor angiogenesis." (PMID 27029061, 2016). "In addition, aberrant activation of NOTCH signaling induced by JAG1 overexpression also predicts poor clinical outcome in breast cancer patients." (PMID 27029061, 2016). "Our results showed that the reduction of SOX2 in KDM2A-depleted breast cancer cells could be fully rescued by ectopic expression of JAG1 suggesting the involvement of NOTCH signaling in the regulation of SOX2 transcription." (PMID 27029061, 2016). "Thus, we establish that BCSC and NOTCH4 activities predict both de novo and acquired tamoxifen resistance and that combining endocrine therapy with targeting JAG1-NOTCH4 overcomes resistance in human breast cancers." (PMID 26387946, 2015). "JAG1 involvement in breast CSC has also been confirmed by mouse models in which mammary-specific deletion of Lfng, an N-acetylglucosamine transferase that prevents Notch activation by Jagged ligands, induces basal-like breast cancer with higher Jag1 activity and enhanced CSC proliferation." (PMID 25309874, 2014). "Furthermore, Jag1 activation in breast cancer cellspromotes their metastasis into the bone in vivo by activating Notch in neighboring bonecells." (PMID 25380226, 2014). "For instance, JAG1 could be repressed by miR-34b in estrogen-dependent breast cancer cells and by miR-524-5p in glioma." (PMID 24659709, 2014). "The KM survival curves showed that CD46, JAG1, IL6, and IL6R were all risk factors that lead to poor prognosis in breast cancer patients, which implies that the enhanced interaction between CD46-JAG1 leads to poor prognosis in breast cancer patients, along with the IL6-(IL6R+IL6ST) axis." (PMID 38571938, 2024). "In vivo leptin signaling inhibition reduced Notch and target expression (NICD1, NICD4, Notch3, JAG1 and survivin), suggesting that leptin-Notch crosstalk could be involved in the reported higher incidence, aggressiveness and poor prognosis of breast cancer in obese patients." (PMID 30004402, 2018). "It has previously been seen that the Notch receptor on breast cancer cells plays an important role in invasion and intravasation in the iTEM assay; therefore we tested whether altering expression of JAG1 in macrophages had an effect on tumor cell transendothelial migration." (PMID 29636067, 2018). "Moreover, TEAD binds to regulatory sequences of the JAG1 gene in human breast cancer cells." (PMID 27554485, 2016). "In metastatic breast cancer cells, NOTCH4, NOTCH3, and JAG1 were found to be upregulated compared to other cancer cell types." (PMID 36605720, 2022).
breast carcinoma (continued). "Both JAG1 (P-value = 0.0002) and DLL1 (P-value = 0.009) showed higher expression in stage I than stage II of breast cancer." (PMID 36476410, 2022). "Earlier studies on human breast cancer cell line MCF-7 and endometrial stromal cells demonstrated that promoter of JAG1 contains estrogen-responsive elements." (PMID 35216398, 2022). "Notch3 and Jag1 are key regulators of CSC renewal and survival during hypoxia in breast cancer and tumours derived from breast cancer cell lines." (PMID 35563449, 2022). "Jagged canonical Notch ligand 1 (JAG1) regulates the progression of many cancers by the Notch signaling pathway, but its role in breast cancer (BC) remains unclear." (PMID 36539520, 2022). "Other groups have reported that RANK signaling is also involved in breast cancer development by mechanisms distinct from ours.68,69) Moreover, we demonstrated that TRAF6-mediated TLR4 signaling also induces JAG1 expression in macrophages." (PMID 33840674, 2021). "In mammary tumor cells, radiation stimulated EMT through the IL-6/JAK/STAT3 signaling axis, which upregulated JAG1, DLL4, and Notch2 transcripts, and GSI addition effectively attenuated migration and mesenchymal markers expression in the irradiated cells." (PMID 34680255, 2021). "In order to investigate the role of linc-OIP5, YAP1, and JAG1 in breast tumorigenesis, their expression levels in normal breast cells (MCF-10) and breast cancer cells (MDA-MB-231, MCF-7) were verified by RT-PCR." (PMID 32046779, 2020). "The expression of jagged 1 (JAG1), one of the Notch ligands, was inhibited with knockdown of TRIB3 in breast cancer cells." (PMID 30678233, 2019). "Notch receptors (Notch 1, 3 and 4) and ligands (JAG1 and DLL4) were highly expressed in human breast cancers, contributing to the abnormal growth of breast cancer cells, when compared to normal breast tissues obtained from the margin of the tumor section." (PMID 30248941, 2018). "Jagged1 (JAG1) is another mediator of bone metastasis, particularly in breast cancer." (PMID 38474093, 2024). "Interestingly, both canonical and non-canonical NF-κB signaling pathways have been implicated to activate the juxtacrine Notch signaling pathway via elevating JAG1 expression, leading to an expansion of BCSC populations in breast cancer." (PMID 35805056, 2022). "JAG1, triggers Notch signaling through cell–cell interaction and promotes cancer progression in several cancer types, such as HCC, gastric carcinoma, glioma, breast cancer, ovarian carcinoma, prostate cancer, and colorectal cancer." (PMID 35054034, 2022). "Activation of JAG1/Notch4 signalling was sufficient to induce endocrine therapy resistance in MCF-7 cells, and tamoxifen resistance could be predicted for in ER+ breast cancer patients using a Notch4/HES/Hey gene signature." (PMID 34295896, 2021). "Furthermore, jagged canonical Notch ligand 1 (JAG1), as a significant ligand of Notch signaling pathway, is firstly reported to be closely with breast cancer." (PMID 33292218, 2020). "In addition, the Si-STAT3 transfection reduced the relative mRNA expression of JAG1 and HES1 in linc00514-OVE breast cancer cells." (PMID 32943090, 2020). "Furthermore, immunohistochemistry analysis of breast cancer tissues showed that YAP1 and JAG1 were differentially expressed in breast cancers with different grades." (PMID 32046779, 2020). "In addition, JAG1 and SOX10 can induce mesenchymal features, and have been found to promote the migratory and invasive abilities of breast cancer cells." (PMID 30602372, 2019). "Indeed, cells co-expressing various epithelial and mesenchymal genes display enhanced JAG1 levels in circulating tumor cell (CTC) clusters and in drug-tolerant breast cancer cells." (PMID 30042822, 2018). "Knockdown of JAG1 in breast cancer cells suppressed bone metastatic ability without impacting on the growth of cultured cells and primary mammary tumors." (PMID 29104587, 2017).
breast carcinoma (continued). "In addition, JAG1, a potent downstream mediator of TGFB1, which promotes osteolysis in breast cancer cells by activating the NOTCH signaling pathway, leads to increased IL6 expression." (PMID 28319320, 2017). "In addition, we tried to elucidate how KDM2A regulates the behaviors of breast cancer cells and identified JAG1 as a key downstream effector for KDM2A to promote stemness and angiogenesis in breast cancer." (PMID 27029061, 2016). "More recent studies showed that leptin induced expressions of Notch1, 3, 4 in breast cancer cells, and inhibition of leptin signaling, led to decreased protein expression levels of NICD1, NICD4, Notch3, JAG1 and survivin as well as reduced mRNA levels of Notch receptors, ligands and targets." (PMID 27185268, 2016). "Finally, but not least, JAG1 has also been shown to be involved in the tissue specificity of breast cancer dissemination since it has been described to have significant roles in metastasis to the bone and brain." (PMID 25309874, 2014). "Moreover, JAG1, a ligand for Notch receptor, was previously found to be upregulated in drug-resistant breast cancer cells, and this CSC-driven drug resistance in ER+ breast cancer was correlated to the interaction of JAG1 and NOTCH4 in association with the Notch signaling pathway." (PMID 33919109, 2021). "This was confirmed with a second breast cancer cell line, BT549, which also showed no enhancement of transendothelial migration when placed in an iTEM assay with macrophages lacking JAG1 expression." (PMID 29636067, 2018). "Continuous A_HSCORE (positive or negative) of Notch1, Notch4, JAG1, OB-R, VEGF and, VEGFR2 were not significantly different among breast cancers irrespective of their expression of ER, HER2 and PR." (PMID 24716804, 2014). "Here we show that NILCO components (Notch1, Notch4, JAG1, DLL4, leptin, OB-R, IL-1R tI) and target molecules (VEGF and VEGFR2) were co-expressed in breast cancer tissues, irrespective of ER, PR and, HER2 statuses." (PMID 24716804, 2014). "Notch signaling has been extensively studied in this context, and several reports have described JAG1 involvement in EMT, invasive potential, and metastasis particularly but not exclusively, in breast cancer." (PMID 25309874, 2014). "Hence, linc-OIP5 in MDA-MB-231 breast cancer cells may act on the upstream of the YAP1/Notch/NRP1 signaling circuit to affect proliferation, migration, and tube formation of co-cultured HUVECs in a non-cellular direct contact way through JAG1 in conditioned medium." (PMID 32046779, 2020).